TRPA1 (transient receptor potential cation channel subfamily A member 1)
Diseases named in the same sentence as TRPA1 in open-access papers (continued):
Sharing a sentence is not in itself a finding about the gene and the disease.
migraine (continued). "Thus, we predict that TRPA1-mediated SFKs activation may promote IL-1β protein expression, which, together with the increased CGRP release observed in this study, forms synergistic effects on TVS sensitization to enhance migraine pain transmission." (PMID 34830154, 2021).
asthma (61 papers, 2011 to 2025). "Studies have shown that polymorphisms in the TRPV1 and TRPA1 are closely associated with the pathophysiological processes of asthma." (PMID 40678720, 2025). "In asthma, characterized by recurrent episodes of wheezing, breathlessness, and coughing, the dysfunction of TRPA1 is linked to heightened responsiveness of the airways." (PMID 39022308, 2024). "In relation to adipose tissue, which is closely linked to obesity-induced asthma, TRPA1 has also been found to be involved in adipose tissue thermogenesis." (PMID 38365763, 2024). "Dysregulation of TRPA1 in both tracts is associated with various disorders such as asthma, Chronic Obstructive Pulmonary Disease, Irritable Bowel Syndrome, and Inflammatory Bowel Disease." (PMID 39022308, 2024). "ALSPAC (Avon Longitudinal Study of Parents and Children) has provided strong evidence for an association between six SNPs at the TRPA1 gene and asthma (rs959974, rs1384001, rs7010969, rs3735945, rs920829, and rs4738202)." (PMID 37185752, 2023). "The TRPA1 polymorphisms also contribute to variations in the control of asthma symptoms including airway inflammation and cough." (PMID 37185752, 2023). "Antagonistic TRPA1 is mainly involved in treating pain, asthma, pneumonia, and other diseases caused by neurogenic inflammation." (PMID 36875034, 2023). "In most of the cells, TRP channels are expressed, and strong evidence for an essential role in airway function and associated diseases, such as CF, asthma, fibrosis and edema was demonstrated for TRPA1, TRPC6, TRPM2, TRPM5, TRPM7, TRPV2, TRPV4 and TRPV6." (PMID 36139480, 2022). "Obviously, new methods for the treatment of asthma exacerbations caused by the influence of temperatures and humidity should be based on regulating the activity of TRPA1, TRPM8, and TRPV channels." (PMID 34356881, 2021). "We demonstrate that an alteration to the putative lipid-binding site containing a residue polymorphism associated with human asthma affects the cold sensitivity of TRPA1." (PMID 32226391, 2020). "Here we describe a thorough characterization of the physiological and behavioral phenotype of rats harboring a null allele of Trpa1 with respect to models of pain, itch, and asthma." (PMID 31969645, 2020). "The role of TRPA1 is also supported by single nucleotide polymorphisms in humans, which are associated with an increased risk for diagnosed asthma." (PMID 31547502, 2019). "Here, we investigate the enhancement of TRPA1 function caused by inflammatory mediators, which is thought to be important in lung conditions such as asthma and COPD." (PMID 28076424, 2017). "We analysed associations between 31 TRPA1 single nucleotide polymorphisms (SNPs) and current doctor‐diagnosed asthma and total IgE concentration at 7.5 years in the Avon Longitudinal Study of Parents and Children (ALSPAC) birth cohort." (PMID 27779810, 2017). "We confirmed that the effect estimates for the association between TRPA1 and asthma were smaller in ALSPAC, and especially in PIAMA, when we analysed ‘ever’ asthma rather than ‘current’ asthma in these cohorts." (PMID 27779810, 2017). "We found strong evidence for an association between TRPA1 polymorphisms and asthma in children at 7–8 years of age in the population‐based ALSPAC birth cohort." (PMID 27779810, 2017). "Whilst a recent study reported correlations between two TRPA1 polymorphisms and asthma control in children with asthma 27, it was underpowered and statistical evidence was weak." (PMID 27779810, 2017). "A large number of recent studies have implicated TRPA1 in the pathogenesis of several respiratory diseases including chronic cough, asthma, COPD, allergic rhinitis and cystic fibrosis." (PMID 27827953, 2016). "Relevant to the context of asthma, TRPA1 channels have been implicated in pain and inflammatory responses in the airways in mice." (PMID 23631390, 2013).
asthma (continued). "Accidental exposure to a number of environmental irritants, many of which are now identified as TRPA1 stimulants, has been reported to cause asthma-like symptoms, a condition that has been defined as RADS." (PMID 22905134, 2012). "A previous study investigated the association between asthma and TRPA1." (PMID 39273183, 2024). "Dysregulated TRPA1 signaling may contribute to exaggerated bronchoconstriction, which is a hallmark of asthma attacks." (PMID 39022308, 2024). "In humans, TRPA1 polymorphisms are associated with reduced asthma control." (PMID 37039840, 2023). "Additionally, studies have shown a correlation between variants of the TRPA1 gene and childhood asthma, further suggesting the participation of this channel in the pathogenesis of asthma." (PMID 37841931, 2023). "There is also evidence that, in humans, TRPA1 polymorphisms correlate with reduced asthma control." (PMID 35562920, 2022). "Moreover, several human TRPA1 gene variants have been associated with diseases, including familial episodic pain syndrome, cramp-fasciculation syndrome, asthma, and cough." (PMID 34768891, 2021). "However, animal studies with genetic ablation or pharmacological inhibition of TRPA1 suggest that the channel is causally involved in airway inflammation under pathological conditions, such as asthma or chronic obstructive pulmonary disease." (PMID 31547502, 2019). "In a population‐based birth cohort, we investigated whether TRPA1 (8q13) gene variants are associated with childhood asthma and IgE concentration, and whether these associations were modified by prenatal exposure to paracetamol." (PMID 27779810, 2017). "We speculate that other prenatal and post‐natal oxidant exposures may be more important than paracetamol as activators of TRPA1, thus contributing to the association we have found between TRPA1 genotype and childhood asthma." (PMID 27779810, 2017). "Beyond its known physiological roles, TRPA1 is implicated in a number of pathological conditions including the generation of asthma, joint oedema, osteoarthritis and skin inflammatory diseases such as acute inflammatory response and allergic contact dermatitis." (PMID 28424320, 2017). "In this review, the roles of naturally occurring flavor and fragrance chemicals in TRPA1 activity associated with allergic disorders, such as asthma, eczema (atopic dermatitis) and allergic rhinitis are discussed along with the rationale for the use of TRPA1 as an anti-allergic target." (PMID 25897313, 2015). "Moreover, studies on asthma exacerbation caused by factors such as PM2.5 pollution suggest that TRPA1 may contribute to enhancing airway inflammation associated with environmental pollutants, further solidifying the involvement of TRPA1 in asthma pathogenesis." (PMID 39273183, 2024). "Furthermore, TRPA1 has been implicated in airway tissue injury, inflammation, and the transition of fibroblasts, thereby posing challenges in conditions, such as severe asthma and fibrosis." (PMID 39022308, 2024). "TRPA1 is expressed on pulmonary innervation - an anatomically relevant region for respiratory diseases and implicated in the orchestration of inflammatory response in animal models of airway diseases, including chronic cough, asthma, COPD, allergic rhinitis and cystic fibrosis." (PMID 27827953, 2016). "These inhibit, desensitize, and downregulate TRPV1/TRPA1, which impacts airway inflammation, hyperresponsiveness, and remodeling, ultimately affecting asthma." (PMID 40678720, 2025). "In this study, we revealed the important role of TRPA1 channels in papain-induced murine asthma models." (PMID 41322401, 2025). "TRPV1/TRPA1-mediated mechanisms tie tear gas injury to pathways involved in acute/chronic pain, cough, asthma, dermatitis, and neurodegeneration; animal models suggest transient receptor potential inhibitors as potential countermeasures." (PMID 41377027, 2025).
asthma (continued). "It is well-known that certain exogenous or endogenous stimuli can trigger asthma responses by activating TRPV1/TRPA1." (PMID 40678720, 2025). "TRPA1 has also been found to be highly expressed in CD4+ T cells within the lung tissue of C57BL/6 mouse asthma models, with expression levels increasing with asthma severity." (PMID 40678720, 2025). "In this paper, we provide an overview of the ameliorative or therapeutic effects of CHM or their extracts on asthma, offering a reference for the development of new drugs modulating TRPV1/TRPA1 for asthma treatment." (PMID 40678720, 2025). "Our results provide scientific evidence to clarify the potential of TRPA1 antagonists as a therapeutic agent for cold air-induced asthma exacerbation." (PMID 41322401, 2025). "TRPV1/TRPA1 mediates the crosstalk between the nervous and immune systems, influencing both acute and chronic symptoms of asthma." (PMID 40678720, 2025). "Increasing evidence suggests that Chinese herbal medicines (CHM) exert beneficial effects in asthma treatment by modulating TRPV1/TRPA1." (PMID 40678720, 2025). "Transient receptor potential channels, specifically vanilloid receptor 1 (TRPV1) and ankyrin 1 (TRPA1), are polymodal sensory channels extensively distributed in the lungs and represent promising therapeutic targets for asthma." (PMID 40678720, 2025). "In mouse models, TRPA1 knockout mice (TRPA1−/−) demonstrated reduced immune cell infiltration in the bronchoalveolar fluid, further supporting the role of TRPA1 in asthma-related inflammation." (PMID 39664985, 2024). "In asthma, TRPA1 mediates airway inflammation and hyper-responsiveness, making it a potential therapeutic target." (PMID 39273183, 2024). "The results showed a close association between TRPA1 and various inflammatory markers such as IL-4 and IL-13, PGD2, and NGF, which are important for asthma development." (PMID 39273183, 2024). "AITC has also demonstrated efficacy in the treatment of allergy-induced asthma by reducing inflammation and airway constriction through modulation of TRPA1." (PMID 39770075, 2024). "AITC has shown efficacy in the treatment of allergy-induced asthma by reducing inflammation and airway constriction through modulation of TRPA1 and ERK signaling and MCP-1." (PMID 39770075, 2024). "The inhibition of TRPA1 selectively reduces pulmonary inflammation and mitigates airway hyperreactivity in mouse and guinea pig models of asthma." (PMID 39022308, 2024). "Dysregulation of TRPA1 in conditions such as asthma and chronic obstructive pulmonary disease (COPD) underscores its significance in respiratory homeostasis and presents opportunities for targeted therapeutic interventions." (PMID 39022308, 2024). "Beyond immediate defense mechanisms, the involvement of TRPA1 in fibroblast-myofibroblast transition and mediation of airway tissue injury underscores its significance in conditions such as severe asthma and fibrosis." (PMID 39022308, 2024). "Dysregulation of TRPA1 in conditions such as severe asthma and fibrosis underscores its significance in airway remodeling and respiratory homeostasis." (PMID 39022308, 2024). "TRPA1 plays an important role in acute and chronic pain, inflammation, kidney disease, cough and asthma, osteoarthritis, cardiovascular disease, obesity, diabetes, and other diseases." (PMID 39735214, 2024). "As the Th1-Th2 paradigm is essential when considering pathogenesis of inflammatory diseases including asthma, we aimed to study the regulation of TRPA1 expression and function under Th1 and Th2-type inflammation in human A549 lung epithelial cells." (PMID 37386145, 2023). "This mutant was discovered in a father-son pair with cramp-fasciculation and other neuronal hyperexcitability-hypersensitivity symptoms including cold hyperalgesia, chronic itch, and asthma that are consistent with aberrant TRPA1 function." (PMID 37208332, 2023).
asthma (continued). "TDI is a TRPA1-dependent inducer of other atopic models such as contact dermatitis, asthma, allergic rhinitis, and chronic itch." (PMID 36877675, 2023). "The reversal of acetylcholine-induced airway hyperreactivity in mice with Ovalbumin-induced allergic asthma with the TRPA1 antagonist HC-030031 indicates the therapeutic potential of TRPA1 in the inhibition of asthma." (PMID 37569884, 2023). "TRPA1 is an ion channel that mediates cough signaling, which is key to the diagnosis and treatment of asthma." (PMID 37039840, 2023). "GDC-0334 is a potent oral TRPA1 antagonist that inhibits the effects of TRPA1 on airway smooth muscles and sensory neurons, reduces edema, dermal blood flow, cough, and allergic airway inflammation, and treats asthma." (PMID 36875034, 2023). "Experiments also supported the role of TRPA1 antagonists or TRPA1 knockout mice in the treatment of Asthma and bronchitis." (PMID 35685622, 2022). "Various noxious chemicals and environmental/industrial irritants that activate TRPA1 function as triggers for airway inflammatory diseases and are known to worsen asthma attacks." (PMID 35562920, 2022). "It has been found that the TRPA1 gene knockout mouse asthma model has reduced inflammatory factors and airway hyperresponsiveness." (PMID 35911969, 2022). "TRPA1 activation contributes to the development of airway hyperreactivity (AHR) in asthma and to the late asthmatic response (LAR)." (PMID 33557843, 2021). "It should be noted that not only features of TRPA1 channel expression in asthma but also the impact of variations in the TRPA1 gene on the development and course of asthma are still far from clear." (PMID 34356881, 2021). "TRPA1 is thought to initiate the asthma episodes via activation by cigarette smoke, chlorine, aldehydes and scents, while TRPV1 regulates inflammation and cell proliferation." (PMID 33803491, 2021). "Evidence for the relationship between TRPA1 SNPs in coding (rs920829, rs959976) and non-coding regions (rs959974, rs1384001, rs7010969, rs3735945, rs920829, and rs4738202) and asthma developing in children aged 7–8 years has been presented." (PMID 34356881, 2021). "TRPA1 have become one of the most promising targets for drug development in chronic cough, asthma, chronic obstructive pulmonary disease (COPD), and allergic rhinitis." (PMID 34356881, 2021). "Together, this further supports nerve targeting approaches such as TRPA1 antagonism as a treatment for asthma." (PMID 33557843, 2021). "The administration of TRPA1 antagonists has been shown to reduce late symptoms of asthma in experimental animals." (PMID 34356881, 2021). "Sensory nerve activation, amongst others via Transient Receptor Potential Ankyrin 1 (TRPA1) channels, contributes to asthma characteristics including cough, bronchoconstriction, mucus secretion, airway hyperresponsiveness (AHR) and inflammation." (PMID 33557843, 2021). "TRPA1 antagonists have been shown to alleviate asthma symptoms in different animal models of asthma." (PMID 33557843, 2021). "TRPA1 is a remarkable airway chemical sensor with roles in both protective reflexes (sneezing, coughing) and pathophysiological responses (inflammation, bronchial hyperreactivity)." (PMID 33803491, 2021). "Little is known on the role of transient receptor potential ankyrin 1 (TRPA1) in fibroblast—myofibroblast transition (FMT) that can lead to airway remodeling which is a major problem for severe asthma and fibrosis." (PMID 33579280, 2021). "LPS-induced bronchial hyperreactivity, myeloperoxidase activity, frequency-decrease were significantly greater in Trpa1−/− mice." (PMID 32526913, 2020). "On the other hand, the infiltration of immune cells into the lung in the rat OVA model of asthma was found to be dependent on TRPA1, supporting the potential use of TRPA1 inhibitors as a therapy for asthma." (PMID 31969645, 2020).
asthma (continued). "Endogenous TRPA1 agonists are also known induce cough, which occurs in response to tissue inflammation in conjunction with diseases such as asthma." (PMID 33193423, 2020). "In murine and rat, ovalbumin-induced models of asthma, a decrease in late asthma response symptoms is seen post TRPA1 antagonist treatment." (PMID 33193423, 2020). "TRPA1 KO rats were largely protected from immune cell infiltration into bronchoalveolar lung fluid in the OVA model of asthma." (PMID 31969645, 2020). "Immune cell infiltration into the lung in the rat OVA model of asthma, on the other hand, appears to be dependent on TRPA1, similar to was has been observed in TRPA1 KO mice." (PMID 31969645, 2020). "We present a detailed phenotyping of the TRPA1 KO rat in models of pain, itch, and asthma that have previously only been investigated in the mouse." (PMID 31969645, 2020). "Here, using CRISPR technology, we have generated a TRPA1 KO rat to enable more sophisticated modeling of pain, itch, and asthma." (PMID 31969645, 2020). "Apart from pain and itch, TRPA1 has also been proposed to contribute critically to airway inflammation in asthma." (PMID 31969645, 2020). "Overall, our study provides a thorough phenotypic mapping of pain and asthma phenotype of the TRPA1 KO rat." (PMID 31969645, 2020). "The same is true for TRPA1 with one drug being successful in the reduction of airway inflammation in a mouse model of asthma." (PMID 30717260, 2019). "We chose three of the most significantly associated SNPs from different LD blocks (rs959974, rs7010969 and rs4738202) to separately estimate the proportion of asthma in the population attributable to TRPA1 genotype (PAF)." (PMID 27779810, 2017). "In Generation R, data on TRPA1 genotype and current doctor‐diagnosed asthma at age 6 years were available for 2073 children, after excluding twins and restricting to Caucasians only, based on genetic ancestry." (PMID 27779810, 2017). "Phenotype of TRPA1 KO mice in allergen-induced asthma model and CS model is in line with this since these animals show reduced leukocyte infiltration in the airways, reduction of cytokine and mucus production." (PMID 27827953, 2016). "α,β-unsaturated aldehydes are earliest recognized TRPA1 activators, and are detected in air spaces, breath, sputum, lungs, and blood from patients with asthma as well as COPD." (PMID 27827953, 2016). "Several TRPA1 activators or sensitizers are endogenously produced in lungs of patients which are also efficient triggers of asthma e.g., H2O2, 4-HNE, cyclic prostaglandin PGJ2 and bradykinin." (PMID 27827953, 2016). "The association between acetaminophen use and the increased prevalence of asthma in children has been attributed to the ability of the reactive drug metabolite, N-acetyl-p-benzoquinone imine, to activate TRPA1 in the airways." (PMID 22905134, 2012). "Despite the fact that TRPA1 is a validated target for neurogenic inflammation, asthma and several types of pain, the number of known selective TRPA1 inhibitors is surprisingly low." (PMID 21291387, 2011). "This study highlighted the perspectives of TRPA1 antagonists for treatment of inflammatory diseases of airways and, particularly, asthma." (PMID 21291387, 2011). "For example, a recent study suggested that TRPA1 plays an important role for airway inflammation and hyperreactivity in a mouse model for asthma." (PMID 21861907, 2011). "Therefore, this study systematically analyzed 134 articles covering the pathogenesis of asthma, current treatment strategies, the role of TRPV1/TRPA1 in asthma, and the modulation of TRPV1/TRPA1 by Chinese herbal medicines in asthma." (PMID 40678720, 2025). "This exposure significantly upregulated TRPV1 or TRPA1 in lung tissue, exacerbating asthma-like pathological features, which could be alleviated by using TRPV1 antagonists such as capsazepine or TRPA1 antagonists like HC030031." (PMID 40678720, 2025).